NPTX2 (neuronal pentraxin 2)
Diseases named in the same sentence as NPTX2 in open-access papers (continued):
Sharing a sentence is not in itself a finding about the gene and the disease.
Stroke (1 paper, 2025). Sudden impairment of blood flow to a part of the brain due to occlusion or rupture of an artery to the brain. "ROC curve analysis was performed to assess the diagnostic accuracy of serum NPTX2 for PSCI at 3 months post‐stroke." (PMID 39924979, 2025). "Correlation between admission serum NPTX2 level and total score and subcognitive domains of MoCA at 3 months of stroke onset." (PMID 39924979, 2025). "Serum NPTX2 levels in AIS patients were positively correlated with 3‐month total MoCA scores after stroke (r = 0.322, p < 0.01)." (PMID 39924979, 2025). "Additionally, while some known confounding factors (e.g., age, gender, stroke severity) were controlled, unmeasured factors like lifestyle or undiagnosed conditions could still influence the relationship between NPTX2 levels and PSCI." (PMID 39924979, 2025).
tumor (20 papers, 2015 to 2025). "The potential association between circulating NPTX2 methylation levels and other circulating tumor biomarkers, such as RAS mutational status and RAS mutant allele fraction in cfDNA, CA19-9 levels or cfDNA concentration, was determined in all 95 liquid biopsy samples." (PMID 37481552, 2023). "Previous studies have suggested that NPTX2 functions as a tumor suppressor in some tumors, and has an oncogenic function in others." (PMID 38254821, 2024). "The NPTX2 (Neuronal Pentraxin 2) gene codes for a protein of the neuronal pentraxin family, whose low expression implies an increase in tumor proliferation and metastasis." (PMID 37481552, 2023). "The results showed that tumor size and tumor weight in the NPTX2 overexpression group were significantly lower than those in the control group." (PMID 35069913, 2022). "miR-1251-5p acted as a tumor inhibitor by inhibiting cell proliferation, migration, and immune evasion by targeting NPTX2." (PMID 35310907, 2022). "By constructing NPTX2-overexpressing cells for colony formation experiments, we found that the formation of tumor spheres was inhibited in the group in which expression of NPTX2 was restored." (PMID 35069913, 2022). "Both transwell and migration assays showed that NPTX2 overexpression markedly promoted tumor cell invasion and migration compared with controls." (PMID 33768003, 2021). "In tumor lesions, CCL4 expression was negatively correlated with the expression of the NPTX2, which implied that NPTX2 potentially participates in immunoregulation in the tumor microenvironment." (PMID 34258887, 2021). "Upregulation of NPTX2 in cold tumor negatively correlated with the expression of CD8A, GZMB, and IFNG, and knockdown of NPTX2 increased the production of CCL4." (PMID 34258887, 2021). "Subsequently, we examined the effect of NPTX2 knockdown on tumor cell metastasis by both transwell and migration assays." (PMID 33768003, 2021). "Both transwell and migration assays showed that NPTX2 overexpression markedly promoted tumor cell invasion and migration, while these promoting effects were also reversed after IL-6-neutralizing antibody treatment." (PMID 33768003, 2021). "As a result, the tumor volume and weight were significantly lower in the mice from sh-NPTX2 group than in those from sh-control group." (PMID 30833544, 2019). "These genes, with the exception of KISS1R and NPTX2, were also upregulated in non-tumor samples from RCC-affected kidneys." (PMID 26317980, 2015). "Collectively, the present results indicate the potential use of NPTX2 as a tumor suppressor in TC." (PMID 38254821, 2024). "Our research uncovered that circ_0054537 regulated RCC malignant progression in vitro and curbed RCC tumor growth in vivo by regulating miR-640/NPTX2 pathway, which may present a potential diagnosis and therapeutic target of RCC." (PMID 34565284, 2021). "First, we used the MTS assay to detect tumor cells’ proliferation activity after NPTX2 knockdown, and the absorbance values were significantly lower than those of the control group, confirming that NPTX2 knockdown inhibits the cell viability of EOC cell lines." (PMID 33768003, 2021). "Moreover, IHC was performed to detect the effects of NPTX2 overexpression or knockdown on tumor tissues." (PMID 33768003, 2021). "NPTX2 knockdown markedly inhibited tumor cell invasion and migration compared with controls." (PMID 33768003, 2021). "Besides, miR-640 downregulation or NPTX2 overexpression partly overturned the tumor suppressor function of circ_0054537 silence and miR-640 overexpression in RCC cells." (PMID 34565284, 2021). "Additionally, NPTX2 promotes tumor cell proliferation and metastasis by activating the NF-κB pathway and the Wnt/β-catenin pathway." (PMID 33013829, 2020).
tumor (continued). "In the second set of experiment, we transplanted sh-NPTX2 or NPTX2-HA CRC cells into the cecum of nude mice to establish an orthotopic tumor model and found that the tumor weight significantly decreased after NPTX2 knockdown but obviously increased after NPTX2 overexpression." (PMID 30833544, 2019). "We performed immunohistochemical staining for two markers of cell proliferation, namely, Ki-67 and PCNA, and found that the staining intensities for Ki-67 and PCNA were weaker in the tumor tissues obtained from NPTX2 knockdown cells than in those obtained from shRNA control cells." (PMID 30833544, 2019). "NPTX2 may function as a tumor suppressor in TC, and have an oncogenic function in NECTT." (PMID 38254821, 2024). "Finally, we marked the biological function of NPTX2 in ccRCC, as our findings showed shRNA-induced knockdown of NPTX2 constrained proliferation, migration, and immune escape of ccRCC cells, which indicated that NPTX2 was a tumor driver in ccRCC." (PMID 35310907, 2022). "Finally, to determine whether NPTX2 can regulate EOC tumorigenesis in vivo, we injected EOC cell lines with NPTX2 overexpression, knockdown or control into the flank regions of nude mice, observed the tumor growths and followed the survival rates." (PMID 33768003, 2021). "Second, as an extracellular protein, NPTX2 may regulate the tumor microenvironment of CRC." (PMID 30833544, 2019). "Treatment with 5-azadC restored NPTX2 expression (mRNA and protein) in PC-3 and DU145 cells, while NPTX2 OE suppressed proliferation and impaired tumor growth in nude mice." (PMID 41008642, 2025). "Neuronal pentraxin 2 (NPTX2), which is the most frequently dysregulated gene in patient tumor tissues." (PMID 34565284, 2021). "In this study, we found that NPTX2 expression was negatively correlated with miR-640, but was negatively correlated with circ_0054537 expression in RCC tumor tissues." (PMID 34565284, 2021). "Overexpression of NPTX2 has been identified as a prognosis factor in clear cell renal cell carcinoma, and its interaction with AMPA-selective glutamate receptor-4 affects tumor cell viability and metastasis." (PMID 33013829, 2020). "The in vitro and in vivo results discovered that circ_0054537 acted as a ceRNA for miR-640 to regulate the expression of NPTX2, thereby regulating cell proliferation, apoptosis, migration, invasion, and glycolysis in vitro, as well as mediate RCC tumor growth in vivo." (PMID 34565284, 2021). "In conclusion, circ_0054537/miR-640/NPTX2 ceRNA pathway regulated RCC malignant progression in vitro and curbed RCC tumor growth in vivo, which could be a potential diagnosis and therapeutic target of RCC." (PMID 34565284, 2021).
cancer (13 papers, 2016 to 2025). A tumor composed of atypical neoplastic, often pleomorphic cells that invade other tissues. "Several studies have shown that expression levels of NPTX2 are associated with the development of various cancers." (PMID 35069913, 2022). "Recent studies also widely reported associations between NPTX2 and cancer progression or treatment response, and high NPTX2 expression was closely related to enhanced cancer cell proliferation, migration, and invasion abilities." (PMID 36015648, 2022). "Taken together, the present study revealed a novel molecule involved in CRC development and highlighted the inverse correlation between individual risk of cancer and nervous system diseases, owing to the differential expression of nerve-related molecules such as NPTX2." (PMID 30833544, 2019). "Recent studies suggested that the aberrant DNA methylation and mRNA and protein expression of NPTX2 affect the progression and prognosis of several cancers." (PMID 38254821, 2024). "Moreover, several studies have also reported that NPTX2 is involved in the occurrence and development of malignant tumors, while it plays a contradictory role in different tumors." (PMID 33768003, 2021). "Furthermore, it may suggest that the impact of NPTX2 hypermethylation differs according to cancer stage." (PMID 29212200, 2017). "Prediction results of the constructed universal model for validating the five additional cancers by using the optimal biomarker combination (ALX3, NPTX2, and TRIM58)." (PMID 39944136, 2025). "The best combination of common methylation biomarkers derived from the five initial cancer types were ALX3, NPTX2, and TRIM58." (PMID 39944136, 2025). "Prediction results of independent prediction models for the five low-survival-rate cancers by using the optimal biomarker combination (ALX3, NPTX2, and TRIM58)." (PMID 39944136, 2025). "The Δβ values of ALX3, NPTX2, and TRIM58 for five low-survival-rate cancers by stage." (PMID 39944136, 2025). "The Δβ values of ALX3, NPTX2, and TRIM58 for five low-survival-rate cancers." (PMID 39944136, 2025).
neurological diseases (9 papers, 2014 to 2025). "Among them, Nptx2, Nedd9, Rorb, Cux2, and Htr3a are involved in neuronal development or associated with neurological diseases." (PMID 25071448, 2014). "Additionally, NPTX2 has also been associated with neuroinflammatory responses that, in turn, are associated with trauma and neurological diseases, as well as with blood‐brain barrier dysfunction." (PMID 40522075, 2025). "Given its central involvement in these processes, NPTX2 has garnered increasing attention in recent years for its potential role in neurodegenerative, neuropsychiatric, and other neurological disorders." (PMID 40694319, 2025). "These modules included synaptic markers that already feature well-described decreases in neurodegeneration, such as VGF and NPTX2, reinforcing their potential as reliable markers of degeneration across different neurologic diseases." (PMID 39107789, 2024). "In recent years, more and more studies on the correlation between NPTX2 and diverse neurological diseases have been reported." (PMID 32748547, 2020). "In conclusion, NPTX2, a molecule related to nervous system diseases, promotes CRC cell proliferation and metastasis through the activation of the Wnt/β-catenin pathway via direct interaction with FZD6." (PMID 30833544, 2019). "Extensive studies have revealed the importance of the NPTX2/NPTXR axis in nervous system diseases, involving recruitment of glutamate receptors and formation of synapses." (PMID 30833544, 2019). "The relationship between NPTX2 and a number of neurological diseases has been widely reported." (PMID 32748547, 2020). "Although some studies have observed fluctuations in the level of NPTX2 in various neurological diseases, the role of NPTX2 in it is largely unknown." (PMID 32748547, 2020). "However, our results indicate that serum NPTX2 is decreased in VaD, which expands the spectrum of neurological diseases that NPTX2 may affect." (PMID 32748547, 2020).
neurodegenerative disease (8 papers, 2020 to 2025). A disorder of the central nervous system characterized by gradual and progressive loss of neural tissue and neurologic function. "NPTX2 (neuronal pentraxin 2) is also a member of the highly conserved pentraxin protein group and was previously associated with neurodegenerative diseases." (PMID 34440356, 2021). "When evaluating synaptic dysfunction biomarkers in CSF, it was demonstrated that SNAP25, 14‐3‐3 zeta/delta, and NPTX2 (neuronal pentraxin), in various combinations, can discriminate AD from other neurodegenerative diseases." (PMID 40613333, 2025). "CART peptide (encoded by Cartpt) has an established role in immunomodulation, whereas our current understandings of Nptx2 functions are limited to synapse formation in normal brain functions and neurodegenerative diseases." (PMID 38109308, 2023). "However, NPTX2 is a promising synaptic biomarker candidate for neuronal degeneration in a range of neurodegenerative diseases." (PMID 40522075, 2025). "Moreover, a recent study demonstrated that neuronal pentraxin 2 (Nptx2) is involved in complement activation and regulates microglia-mediated synapses in neurodegenerative diseases." (PMID 37815901, 2024). "While NPTX2 remains a promising surrogate marker of inhibitory circuit dysfunction in AD, DS, and other neurodegenerative diseases, VAMP-2 may be a better surrogate marker of cognitive performance in adults with DS." (PMID 34183050, 2021).
infection (3 papers, 2017 to 2022). The state of being infected such as from the introduction of a foreign agent such as serum, vaccine, antigenic substance or organism. "Immunohistochemical staining revealed that lentivirus infection was successful in the NPTX2 overexpression group, while NPTX2 was highly expressed in DU145 cells, and there was less positive expression of Ki67 in NPTX2-overexpressing tumors than in control tumors." (PMID 35069913, 2022).
NPTX2 also shares sentences with these, for which no sentence is quoted: Leigh syndrome (5 papers); neuropathy (5); Ataxia (3); cognitive disorder (3); Dementia with Lewy Bodies (3); retinitis pigmentosa (3); ischemia (2); MELAS (2); mitochondrial disease (2); rectal cancer (2); Sengers syndrome (2); amyotrophic lateral sclerosis (1); Atrophy (1); autism spectrum disorder (1); Barth syndrome (1); bladder cancer (1); brain tumor (1); carcinoid (1); chronic headache (1); cyst (1); Encephalopathy (1); endometrial cancer (1); epilepsy (1); Fibroadenoma (1); Friedreich ataxia (1); Hypertension (1); Kearns-Sayre syndrome (1); leiomyoma (1); lung adenocarcinoma (1); malignant glioma (1).
A further 20 diseases each share a sentence with NPTX2 in 1 paper.